MUC5B (mucin 5B, oligomeric mucus/gel-forming)
Diseases named in the same sentence as MUC5B in open-access papers (continued):
Sharing a sentence is not in itself a finding about the gene and the disease.
pulmonary fibrosis (continued). "Also, it was demonstrated that a gene promoter variant (rs 35705950) encoding mucin 5B (MUC5B) increases its expression and increases the risk of pulmonary fibrosis." (PMID 40497957, 2025). "For sex-specific GWAS, a GWS association specific to males was found between MUC5AC and MUC5B, which highly colocalizes with a MUC5B eQTL in lung tissue and many studies have linked this variant to pulmonary disease like idiopathic pulmonary fibrosis and COVID-19." (PMID 39132489, 2024). "Instead of using the term ‘idiopathic’, categorizing pulmonary fibrosis based on high-risk genomic pulmonary fibrosis, MUC5B-pulmonary fibrosis, or telomeropathy-pulmonary fibrosis may offer a more effective approach." (PMID 38680944, 2024). "As the honeycombing is also diagnosed in chronic fibrotic HP and in other fibrotic ILDs, it is reasonable to speculate that the MUC5B polymorphism may have a pathogenic influence on lung fibrosis development in these conditions." (PMID 37445925, 2023). "The influence of MUC5B polymorphism on the development and progression of lung fibrosis was extensively investigated in idiopathic pulmonary fibrosis (IPF), as the bronchioloalveolar epithelial injury is the main pathogenic mechanism of progressive lung fibrosis in this disease." (PMID 37445925, 2023). "Airway mucociliary dysfunction caused by high concentration of MUC5B in airways may be highly correlated with the persistent development of pulmonary fibrosis." (PMID 35111363, 2022). "However, the MUC5B variant is associated with a reduced risk of severe COVID-19 (OR = 0.89), suggesting the risk allele’s opposing effect for infection and pulmonary fibrosis." (PMID 35482673, 2022). "This study aimed to identify whether risk alleles of known genes linked with emphysema (SERPINA1) and pulmonary fibrosis (MUC5B) are associated with severe COVID-19, and whether plasma mucin 5B differs according to patients’ outcomes." (PMID 35892712, 2022). "MUC5B was associated with pulmonary fibrosis idiopathic (FDR = 0.013961)." (PMID 34545326, 2021). "A common variant in the promoter region of MUC5B gene has been identified as the strongest genetic risk factor for sporadic and familiar pulmonary fibrosis, although its role in disease development remains speculative." (PMID 33794872, 2021). "Muc5b overexpression causes mucociliary dysfunction and enhances lung fibrosis in mice." (PMID 32724493, 2020). "In addition to Muc5b, we evaluated transcript levels of a panel of 12 genes recently identified as risk factors for pulmonary fibrosis in genome wide association studies in patients." (PMID 32332792, 2020). "Recently, we reported that a single nucleotide variant (SNV) rs35705950 in the upstream region of MUC5B gene, the strongest susceptibility variant to idiopathic pulmonary fibrosis (IPF), was associated with ILD in the patients with rheumatoid arthritis (RA) in a multinational collaborative study." (PMID 33076992, 2020). "For example, rs 35705950, a common polymorphism in the promoter of Mucin 5B (MUC5B), is associated with familial interstitial pneumonia and idiopathic pulmonary fibrosis, which suggests a crucial role of dysregulated MUC5B expression in the pathogenesis of pulmonary fibrosis." (PMID 32082621, 2019). "The use of this MUC5B promoter variant to identify individuals in the preclinical stages of pulmonary fibrosis may be ideal for early interventions focused on avoiding the development of extensive, permanent and irreversible lung remodelling." (PMID 31514468, 2019). "Our findings suggest that mucociliary dysfunction might play a causative role in bleomycin-induced pulmonary fibrosis in mice overexpressing Muc5b, and that MUC5B in distal airspaces is a potential therapeutic target in humans with IPF." (PMID 30560893, 2018).
pulmonary fibrosis (continued). "In a study of individuals with lung disease, a genome-wide linkage scan showed that a common promoter of MUC5B was associated with familial interstitial pneumonia and idiopathic pulmonary fibrosis; MUC5B was highly expressed among diseased individuals, compared to controls." (PMID 28346466, 2017). "More recently, extensive phenotyping of first-degree relatives of patients with FIP revealed evidence of dysfunction in pathways associated with the development of pulmonary fibrosis, including telomere shortening, endoplasmic reticulum stress, and elevated MUC5B levels." (PMID 26400796, 2015). "The association of the MUC5B promoter polymorphism appears to be specific to pulmonary fibrosis." (PMID 26400796, 2015). "MUC5B rs35705950 in one report was found to be protective in terms of COVID-19 hospitalization, but not severity, and it was associated with less severe disease according to another publication, although carriers of the minor variant are known to be more susceptible to idiopathic pulmonary fibrosis." (PMID 39752416, 2025). "The authors hypothesized that “attrition of SASCs is a common feature of risk and development of lung fibrosis” and proposed that “the MUC5B variant potentially deregulates MUC5B silencing and locks in mucosecretory differentiation of SASC cells mobilized by injury”." (PMID 39311112, 2024). "Therefore, MUC5B polymorphism may be considered a marker of preclinical pulmonary fibrosis, enabling the identification of the cohort of people at an increased risk of IPF development." (PMID 37445925, 2023). "A common single nucleotide polymorphism (SNP) in the putative promoter region of the mucin 5B (MUC5B) gene (rs35705950), which encoded a glycosylated macromolecular component of mucus, has been associated with familiar pulmonary fibrosis and sporadic pulmonary fibrosis." (PMID 34200784, 2021). "This latter point is demonstrated in those with mutations in the MUC5B promoter (variant rs35705950; }) or surfactant proteins that increase protein retention through increased production to promote susceptibility to interstitial pneumonia and eventually idiopathic pulmonary fibrosis." (PMID 28384302, 2017). "A Japanese study demonstrated that mucin 5B (MUC5B) promoter polymorphism is associated with an increased risk of ILD, more severe lung involvement, and increased pulmonary fibrosis in patients with MPO-ANCA vasculitis." (PMID 40649005, 2025). "As a potential biomarker for pulmonary fibrosis, MUC5B faces several challenges in the process of clinical translation." (PMID 40351459, 2025). "Mutations in telomere-related genes and surfactant proteins have been linked to familial pulmonary fibrosis, while variants in MUC5B and TOLLIP increase the risk of ILD, including idiopathic pulmonary fibrosis and rheumatoid arthritis-associated ILD." (PMID 39768847, 2024). "The total number of all inflammatory cells and lymphocytes was significantly elevated in both WT and MUC5B rs35705950 transgenic mice with lung fibrosis compared to their respective saline control groups." (PMID 39329706, 2024). "One of them is Mucin-5B (MUC5B) associated with familial interstitial pneumonia and idiopathic pulmonary fibrosis." (PMID 39457608, 2024). "This study demonstrates that the overexpression of mucin in the proximal airways, associated with the human MUC5B [rs35705950] T allele mutation, confers protection against inflammation and fibrosis in the mouse model of BLM-induced pulmonary fibrosis." (PMID 39329706, 2024). "Pre-clinical studies utilizing these transgenic mice have shown that they develop significantly more severe lung fibrosis than their WT counterparts, which typically express MUC5b in the larger bronchial airways." (PMID 39329706, 2024). "MUC5B polymorphism was found much more frequently in IPF patients than in healthy population, and was an established risk factor for lung fibrosis development and progression." (PMID 37445925, 2023).
pulmonary fibrosis (continued). "MUC5B and SFTPD are considered interesting loci associated with COVID-19 severity, and both genes are strongly correlated with pulmonary fibrosis onset." (PMID 37328761, 2023). "A common polymorphism in the promoter of Mucin 5B, encoded by the gene MUC5B, is associated with both FIP and sporadic pulmonary fibrosis." (PMID 36836843, 2023). "In bleomycin-induced pulmonary fibrosis, the concentration of MUC5B in airways is directly related to the severity of pulmonary fibrosis." (PMID 38255185, 2023). "Meanwhile, the over-expressed MUC5B protein in the distal airway and alveolar cavity had also been considered to be closely related to the development of idiopathic pulmonary fibrosis (IPF)." (PMID 36733806, 2022). "The promoter polymorphism, rs35705950, within the mucin 5B (MUC5B) gene has been associated with both sporadic IPF and familial pulmonary fibrosis in several independent cohorts." (PMID 36555528, 2022). "Indicating that this likely applies to lung fibrosis as well, MUC5B overexpression in distal airways has been shown to significantly impair mucociliary clearance and aggravate lung fibrosis in the mouse model of bleomycin-induced lung injury." (PMID 35326501, 2022). "As MUC5B is a gene extensively studied for its role in lung fibrosis, in future studies, the modification of the gene expression in humans by silica exposure should be considered." (PMID 36672608, 2022). "Among the respiratory conditions, only idiopathic pulmonary fibrosis (IPF) and chronic alveoli lung disease had shared associations with the variants near genes MUC5B, CRHR1, and NSF." (PMID 35482673, 2022). "It was reported that elevated concentrations of MUC5B leads to mucociliary clearance dysfunction and enhances lung fibrosis in mice." (PMID 35770160, 2022). "Of note, this concept is consistent with studies in Muc5b-overexpressing mice that exhibit impaired mucociliary clearance and develop more severe bleomycin-induced pulmonary fibrosis." (PMID 34200296, 2021). "Our previous study showed that in adult mice, conditional Nedd4-2-deficiency in club and alveolar epithelial type II (AE2) cells results in impaired mucociliary clearance, accumulation of Muc5b and progressive, terminal pulmonary fibrosis within 16 weeks." (PMID 34299227, 2021). "The variants involved two genes associated with surfactant metabolism dysfunction (ABCA3 and CSF2RB), two with pulmonary fibrosis (MUC5B and SFTP), one with bronchiectasis (SCNN1B), and one with alpha-1-antitrypsin deficiency (SERPINA1)." (PMID 33526882, 2021). "Among the respiratory conditions, only idiopathic pulmonary fibrosis (IPF) and chronic alveoli lung disease had associations with the variants near genes MUC5B, CRHR1, and NSF." (PMID 34642702, 2021). "The exact function of SPC and MUC5B in lung fibrosis is still under investigation, while the latter three genes have been found to be linked to premature senescence of AEC2." (PMID 33117807, 2020). "In PQ poisoning patients, the concentration of MUC5B in the plasma was increased and correlated to the prognosis of the patients, and these results were consistent with findings from a study of idiopathic pulmonary fibrosis (IPF) patients." (PMID 32724493, 2020). "Genomic analysis has revealed several genetic variants correlated with lung fibrosis, such as surfactant protein C (SPC), MUC5B, telomerase reverse transcriptase (TERT), telomerase RNA component (TERC) and regulator of telomere elongation helicase 1 (RTEL1)." (PMID 33117807, 2020). "Numerous reports link a dysregulation of the gel-forming mucin MUC5B in human lung diseases like asthma, cystic fibrosis, diffuse panbronchiolitis and familial and sporadic and interstitial pneumonia idiopathic pulmonary fibrosis." (PMID 31699684, 2019).
pulmonary fibrosis (continued). "A single nucleotide polymorphism in the promoter region of the MUC5B gene has been linked to the development of familial interstitial pneumonia and sporadic idiopathic pulmonary fibrosis and it has been suggested that this polymorphism might be associated with overexpression of MUC5B in the lung." (PMID 31699684, 2019). "Taken together, the studies indicate the important role of cytokines above and their related downstream signaling molecules in the overexpression of MUC5B in pulmonary fibrosis." (PMID 31309122, 2019). "The increase in fibrosis and decrease in mucociliary transport associated with elevated Muc5b levels led us to investigate whether therapeutic agents predicted to accelerate mucus clearance would be effective in improving outcomes in the SFTPC-Muc5bTg mouse model of lung fibrosis." (PMID 30560893, 2018). "We also establish the ability of the mucolytic agent P-2119 to restore MCC and to suppress bleomycin-induced lung fibrosis in the setting of Muc5b overexpression." (PMID 30560893, 2018). "In patients with IPF, excess MUC5B protein is especially observed in epithelial cells in the respiratory bronchiole and honeycomb cyst, regions of lung involved in lung fibrosis." (PMID 30560893, 2018). "There are many candidate genes implicated in pulmonary fibrosis, such as IGF-I, IGFBPs, ELMOD2, TERT, TERC, SFTPC, SFTPA2), and MUC5B." (PMID 26447616, 2015). "Notably, RA-ILD shares several risk factors with idiopathic pulmonary fibrosis (IPF), namely male gender, smoking history, usual interstitial pneumonia (UIP) pattern of fibrosis, and association with the MUC5B rs35705950 polymorphism." (PMID 40066169, 2025). "Another recent study of relatives from familial interstitial pneumonia (FIP) cohorts found that those with preclinical pulmonary fibrosis (mean age ~66 years) had a higher frequency of the MUC5B rs35705950 variant than relatives without abnormalities on HRCT." (PMID 40999395, 2025). "The role of genetic variants in Mucin-5B (MUC5B) and telomerase reverse transcriptase (TERT) in idiopathic pulmonary fibrosis (IPF) pathogenesis, as well as their associations with clinical characteristics, remain uncertain and may exhibit ethnic variations." (PMID 40999395, 2025). "Therefore, MUC5B is not only a biomarker for diagnosis and prognosis but also holds promise as a potential therapeutic target for pulmonary fibrosis." (PMID 40351459, 2025). "It was shown, that dysregulated MUC5B expression in the lung may be involved in the pathogenesis of pulmonary fibrosis." (PMID 39457608, 2024). "The current study investigates whether mucin overproduction is associated with the human MUC5B [rs35705950] variant in the proximal airways, conferring protection against BLM-induced lung fibrosis in mice." (PMID 39329706, 2024). "Notably, MUC5B rs35705950 TG mice with lung fibrosis exhibited markedly reduced PDGF, CTGF, and IL-13 levels compared to their WT counterparts." (PMID 39329706, 2024). "However, these cell counts were markedly lower in the human MUC5B rs35705950 TG mice with lung fibrosis (h-rs35705950-Tg/BLM) than in their WT counterparts." (PMID 39329706, 2024). "Finally, polymorphisms of mucins, i.e., MUC5B or Toll-like receptor inhibitors (TOLLIP), have been associated with a greater risk of developing pulmonary fibrosis." (PMID 36553114, 2022). "How MUC5B exactly is involved in ILD susceptibility is still an unanswered question, but it highlights a potential role for the distal airways and mucus overproduction in the pathogenesis of pulmonary fibrosis." (PMID 35651878, 2022). "Even beyond the potential influence of the genetic factor of MUC5B SNP rs2943512, whether high glucose itself could cause the over-expression of MUC5B to mediate ATII cells injury and thus trigger pulmonary fibrosis is unclear." (PMID 36733806, 2022). "But the direct cytotoxic effect of MUC5B on ATIIs in pulmonary fibrosis remains indistinct." (PMID 35111363, 2022).
pulmonary fibrosis (continued). "Moreover, ectopic alveolar expression of Muc5b enhances the development of bleomycin-induced lung fibrosis in mice." (PMID 36291184, 2022). "Whether and to what extent MUC5B accumulation influences the development of lung fibrosis remains to be determined." (PMID 35328744, 2022). "The MUC5B promoter polymorphism is a very specific predictive factor for the presence of pulmonary fibrosis as it is only associated with pulmonary fibrosis and not with other chronic respiratory diseases." (PMID 35651878, 2022). "This study also supports the previous finding that high levels of NFkB, TNF, SFTPC, MUC5B, and other proteins could promote lung fibrosis." (PMID 33362771, 2020). "Overexpression of MUC5B induces impaired mucociliary clearance and enhances lung fibrosis in mice." (PMID 32941426, 2020). "Polymorphisms rs2735727 (12/103) and rs12417955 (4/103) that lead to alternative splicing of MUC5B and rs56367042 (3/103) are speculated to be involved in the pathogenesis of idiopathic pulmonary fibrosis." (PMID 33101356, 2020). "Considering the polymorphism in the MUC5B promoter region in some patients with sporadic IPF and familial pulmonary fibrosis, further studies are necessary to determine how ROS adversely impacts the MUC5B gene and its protein product in the development of pulmonary fibrosis in humans." (PMID 31309122, 2019). "However, at present, only a few transcriptional factors have been tested experimentally in the context of their involvement in MUC5B expression regulation in a variety of diseases including cancer and lung fibrosis." (PMID 31309122, 2019). "In human IPF lung tissue, we found that MUC5B is co-expressed with surfactant protein C in columnar epithelial cells lining honeycomb cysts and in type 2 alveolar epithelia, indicating that cell types involved in lung fibrosis in the distal airspace also express MUC5B." (PMID 30560893, 2018). "Our findings suggest that targeting MUC5B in the terminal airways of patients with preclinical stages of interstitial lung disease represents a rational strategy to prevent the progression of preclinical pulmonary fibrosis." (PMID 30560893, 2018). "For example the MUC5B promoter region polymorphism (rs868903), which was strongly associated with familial and idiopathic pulmonary fibrosis, was not identified as a susceptibility locus for SSc or SSc–associated interstitial lung disease." (PMID 26792595, 2016). "Meanwhile, in the field of idiopathic pulmonary fibrosis (IPF), it has been revealed that some genetic backgrounds, such as telomere length, telomerase mutation, and MUC5B promoter polymorphism, are associated with the development of fibrosis in the white population." (PMID 27225339, 2016). "This discovery was further validated in seven independent non-Hispanic white cohorts, and the MUC5B promoter polymorphism remains the strongest and most replicated genetic risk factor for pulmonary fibrosis." (PMID 26400796, 2015). "Several studies reported that the T allele of MUC5B rs35705950 was associated with idiopathic pulmonary fibrosis but not with the development of lung fibrosis in systemic sclerosis or sarcoidosis." (PMID 25121989, 2014). "As MUC5B, SFTPC, and SFTPA1 are expressed by alveolar type II cells, this raises the possibility that injury of these cells is a critical pathogenic mechanism in pulmonary fibrosis." (PMID 24391588, 2013). "A polymorphism on the MUC5B promoter (rs35705950) has been associated with idiopathic pulmonary fibrosis (IPF) but not with systemic sclerosis (SSc) with interstitial lung disease (ILD)." (PMID 23940607, 2013). "The rs35705950 mutant allele is associated with up-regulation of MUC5B expression in the lung, specifically in lesions of IPF, suggesting that dysregulated MUC5B expression in the lung may be involved in the pathogenesis of pulmonary fibrosis." (PMID 23075428, 2012).